IL6 (interleukin 6)
Diseases named in the same sentence as IL6 in open-access papers (continued):
Sharing a sentence is not in itself a finding about the gene and the disease.
infection (continued). "In addition, secretion of IL-6 was dependent on MOI, suggesting that infection at a higher MOI promoted a stronger immune response." (PMID 37629104, 2023). "IL-6 concentrations were already significantly elevated in the supernatants at 8 hpi during infection with the moderately virulent strain 8067 and non-virulent strain T15 and remained elevated at 24 hpi." (PMID 38276150, 2023). "IL-8 has kinetic characteristics very similar to those of IL-6 and, like this, can increase in newborns regardless of the presence of an infection." (PMID 37627653, 2023). "At 24 h post-infection pH1N1/09 did not significantly induce IL-6, IL-8 or TNF, whereas H3N2 resulted in significant expression of all three cytokines in obese and non-obese subjects." (PMID 37857661, 2023). "The levels of IL-6, IL-10 and IL-12p70 were low and not significantly different in BM supernatants during and after the infection." (PMID 37539049, 2023). "Therefore, the innate response to in vitro infection of macrophages with both LAMV and WT MeV includes production of IL-6 and TNFα and activation of the NLRP3 inflammasome to release IL-1β and IL-18." (PMID 36851476, 2023). "ACV effectively induced immunity against Eimeria, as evidenced by reduced oocyst shedding and less intestinal lesions, decreased levels of pro-inflammatory interleukin-6, and improved BWG during both the post infection (PI) period (21–35 days) and the entire growth period." (PMID 37763330, 2023). "Treatment with CNP-miR146a four hours after infection resulted in significantly decreased relative gene expression of TRAF6 (p = 0.01), NF-κB (p = 0.003), IL-6 (p = 0.01), MIP-2 (p = 0.005), IL-1β (p = 0.01), and TNFα (p = 0.003) compared to untreated, MRSA-infected lungs." (PMID 37765178, 2023). "have shown that primary neurons from human angiotensin-converting enzyme 2 (ACE2)-expressing mice produce cytokines (e.g., interferon-α (IFN-α), C-X-C motif chemokine ligand 10 (CXCL10), CCL2, IL-6, and TNF-α) after infection with severe acute respiratory syndrome coronavirus 2 (SARS−CoV−2)." (PMID 37767094, 2023). "After 9 h of infection, V. vulnificus-injected skeletal muscle tissues exhibited edema and neutrophil infiltration and exhibited a high transcriptional level of MIP-2, TNF-α, and IL-6." (PMID 36939368, 2023). "IL-6 and tumor necrosis factor (TNF)-alpha was also higher in the infection group." (PMID 36895535, 2023). "Serum IL-6 > 50.45 pg/mL indicates that the probability of KFD may be small, and sJIA, KD, and infection should be excluded first." (PMID 37608293, 2023). "Inflammatory biomarkers such as WBC, Neutrophils, CRP, IL-6, PCT and ESR could be used to distinguish between non-infection and mild infection, indicate severity of foot ulcer infection and monitor response of anti-infective therapy." (PMID 37065766, 2023). "Furthermore, in our experiment, inflammation-related indicators in blood, such as WBC, CRP, IL-6, IL-1β and TNF-α, exhibited varying degrees of elevation since 18 h of infection." (PMID 37587524, 2023). "However, at 30 days post-infection, TNF-α, IL-6, KC, CCL3, CCL2, CCL20, CXCL11, CCL11), CCL27, CXCL5, CXCL12 and CCL5 were all significantly higher in the BAL fluid of Duox1 KO compared to WT mice." (PMID 36936954, 2023). "While baseline levels of cytokines were increased among patients with sternal infection, at discharge only the level of interleukin 6 remained high compared to no infection groups." (PMID 37637509, 2023). "Levels of proinflammatory chemokines and cytokines CXCL1, CCL5, IFN-γ, IL-1β, CXCL10, IL-17, TNF-α and IL-6 were also assessed in the brain, spleen and liver of MAYV-infected mice throughout the infection." (PMID 36902230, 2023). "Only IL-6 levels were slightly increased after infection at 3 dpi, suggesting that the GD-H3N8 isolate did not induce a severe inflammatory response in the lungs of mice." (PMID 40303727, 2023). "IL-6 and CXCL1 concentration were measured after 12 h of infection." (PMID 36604750, 2023).
infection (continued). "However, the levels of IL-6 were reduced in infected MFD-fed mice compared to uninfected MFD-fed mice during both acute and chronic stages of infection." (PMID 36676177, 2023). "Furthermore, they found that conjunctival cells upregulated TNF, interleukin-1 (IL-1), interleukin-6 (IL-6), and NF-Kβ activity and downregulated antiviral IFN signalling, preventing active infection from ensuing after viral entry." (PMID 37138096, 2023). "Indeed, GSEAs showed a downregulation of gene sets such as TNF-alpha signalling via NF-κB, IL-6/JAK/STAT3 signalling and inflammatory response after infection with the low-virulence isolate at an early stage of infection." (PMID 37520552, 2023). "Additionally, they found within the first 24 hours of infection, expression and secretion of inflammatory cytokines (TNF and IL-6) within the kidney and recruitment of neutrophils to the kidney are enhanced in C3aR−/− mice, compared to WT." (PMID 35925892, 2022). "In addition to IL-6, CXCL1 and CCL2, IL-1β protein levels in PGRN KO kidney were also significantly lower than WT mice at day 9 post-infection when significantly lower fungal burden was observed in PGRN KO mice." (PMID 36121866, 2022). "To further investigate this finding in WT mice, we generated resistant WT mice through the early administration of IFN‐α/β (at 18 h p.i.), which either was or was not followed by a late‐IL‐6 treatment at day three post YM infection." (PMID 35635376, 2022). "In response to bacterial infection, interleukin-6 (IL-6), tumor necrosis factor-α (TNF-α), and interleukin-1β (IL-β) induce PCT synthesis in extrathyroidal tissue with a peak at 6 h from the onset of infection and a half-life of 24 h." (PMID 36139922, 2022). "Similar to their inbred counterparts, outbred SPexp mice had increased proinflammatory cytokines (IL-2, IL-6, TNF-α, and IFN-γ), decreased cellularity in the blood, and an increased frequency of Ag-experienced CD4 and CD8 T cells within PBL 5 d after last infection, as seen in inbred SPexp mice." (PMID 35878936, 2022). "In addition, even though it failed to reach a statistical significance, there was a similar trend for the increased IL-6 in plasma of aged mice and its reduction after AAV-LAV-BPIFB4 infection." (PMID 35087020, 2022). "At this point, we could speculate that these results may be also due to a potential increase in IL-6 and IL-10 levels in the serum of previously infected SARS-CoV-2 females compared to the infection-naive group, as it was observed in a previous study." (PMID 36560410, 2022). "In addition, aged ferrets showed high expression of chemokines (CCL4 and CXCL10) and inflammatory cytokines (IFNB1, IL1B, IL6, and IL7) in the early phase of infection." (PMID 35013229, 2022). "The cytokines TNF-α, IL-6, IL-18, IFN-β, IFN-γ, and CSF3 produced by macrophages play important roles in the protection again pathogens by promoting phagocytosis and mediating the recruitment and activation of effector immune cells into the site of infection." (PMID 37431006, 2022). "As non-specific biomarkers, the levels of CRP and IL-6 are commonly used to assess the presence and severity of acute and chronic inflammation, infection, tissue damage, and cancer." (PMID 35756643, 2022). "Unlike in the liver, where Il6 mRNA abundance was not increased during infection, Il6 mRNA increased in abundance by >8-fold in the spleen." (PMID 35384718, 2022). "Moreover, it was observed that the expression of IL-12, IL-6, TNF-α, HLA-DR, and CD40 by monocytes-derived DCs was drastically reduced after infection." (PMID 35720410, 2022). "Notably, infection with Ado-LOXIN decreased the pattern of expression of TNF-α and IL-6 expression in liver parenchyma of HFD mice compared with ND mice and Ado-null." (PMID 35806336, 2022). "The IL-6 levels also increased with the time of infection but did not vary between WT and complement knockout (C3-/- and C5aR1-/-) mice groups." (PMID 36211424, 2022).
infection (continued). "Similar to H37Ra infection, we found that AM failed to produce cytokines, including IL-12p40, IL-6 and IL-10, but not TNFα, in response to H37Rv infection." (PMID 36776396, 2022). "Recent work by Zheng and colleagues provided genetic evidence that the TLR2 pathway contributes to overwhelming production of inflammatory cytokines (particularly TNF-α, IL-6 and IFN-γ) during infection by SARS-CoV-2 and other β-coronaviruses, following recognition of the E protein." (PMID 35632741, 2022). "Correlation of post-infection sampling time points with plasma cytokine levels from both cohorts showed no clear time-dependent decrease of IL-1β, IL-6, and TNF plasma levels in participants with PASC." (PMID 35732153, 2022). "In addition, expression of pro‐inflammatory cytokines including IL‐6 and TNF was slightly downregulated upon infection while BCR‐signalling genes were significantly upregulated." (PMID 34169553, 2022). "Proinflammatory cytokines, such as IL-6, TNF-α, and IL-1β, have been shown to play a guiding role in the production of antimicrobial cytokines or other effector molecules and contribute to resolving infections." (PMID 35370996, 2022). "However, the expression profile of TNF-α, IFN-α, IL-6, IL-12 and RANTES 6 h post-infection was similar for both C1q-treated H1N1 and H3N2 subtypes." (PMID 35328462, 2022). "TNF-α was only significantly increased at 6 d.p.i; IL-6 was significantly increased at 3 and 6 d.p.i; IFN-γ and NOX2 were significantly increased at 3 and 6 d.p.i, and CD69 showed persistent elevation over the 6 days of infection." (PMID 35930608, 2022). "Our results are in line with those from the literature, where the increased expression of IL-6 was reported in BEAS-2B cells, a human bronchial epithelial cell line, after infection with HAdV3 and HAdV7, and in primary human bronchial epithelial cells infected with HAdV-B14p1." (PMID 35458402, 2022). "Consequently, PRV-∆UL13 infection enhanced the induction of IFNB1 and downstream ISGs, as well as the key inflammatory mediators, including IL6 and TNF." (PMID 35891444, 2022). "During the assessment of the patients on the first day, vital signs (heart rate, blood pressure), infection indicators (WBC, PCT), inflammatory indicators (TNF-α, IL-10, IL-6), CVP, Norepinephrine (NE), oxygenation index (OI), CTNI, and NT-pro BNP were collected." (PMID 35729330, 2022). "This infection is generally characterized by inflammatory cytokines interleukin-1 beta (IL-1β), tumor necrotizing factor alpha (TNF-α), interleukin-6 (IL-6), chemokine (CX-C motif) ligand 2 (CXCL2), and IL-8 (also known as chemokine (CX-C motif) ligand 8-CXCL8)." (PMID 35053737, 2022). "Together, these data suggest that ferrets infected with a high dose of M. tuberculosis mount stronger pro-inflammatory responses in the lungs in the form of elevated expression of the genes for IL-6, IL-17, CXCL10, IFN-γ, and CCL5, as compared to the medium and low-dose infection groups." (PMID 36051240, 2022). "Infection with SARS‐CoV‐2 (MOI = 2) showed that knockdown of ZBP1 attenuated the expression of the measured cytokine genes, as well as the production of CXCL10 and to a lesser degree of IL‐6." (PMID 36268590, 2022). "Infection of intestinal epithelial cells with S. Typhimurium significantly induced the secretion of IL-6 compared to the controls (i.e., non-infected cells)." (PMID 35406099, 2022). "In particular, the transcription level of some cytokines in the splenic lymphocytes, including IL-1β, IL-6, IL-8L1, and CCL4, which are related to B cell activation and antigenic signal transduction to T cells, were significantly upregulated by MDV/CVI988 infection compared with MDV/RB1B infection." (PMID 36680047, 2022). "Notably, we found that the expression of specific markers of M1 type microglia (Aif1, Cd86, Cd40, Ccl2, Ccr2, Cx3cr1, IL-1β, IL-6, and NOS2) was elevated post infection." (PMID 36618398, 2022).
infection (continued). "No detectable levels of IL-6 and IL-8 were found in sera after Vir-S74-T3Bo infection (data not shown)." (PMID 36466866, 2022). "We examined the expression of IL-1β, IL-6 and TNF-α after infection with S. aureus." (PMID 35624447, 2022). "In the study, we showed increased circulating concentrations of 47 inflammatory proteins in patients with severe infection compared to healthy controls, with the most robust increase in the circulating concentration observed for TNFSF14, OSM, CCL23, IL-6, and HGF." (PMID 36209073, 2022). "After EVA71 infection, susceptible cells and nonspecific immune cells are stimulated first to produce cytokines such as TNF-α and IL-6." (PMID 36036059, 2022). "No expression of IL-6 mRNA was detected 2 h post-infection in ghA- and ghC-treated samples at the 6 h timepoint." (PMID 35328462, 2022). "In addition, ELISA results (proinflammatory cytokines IL-6 and TNF-α detected in cell supernatant) showed the downregulation of IL-6 and TNF-α in the MLA and MEM groups compared to the E44 infection group (p < 0.01)." (PMID 36289622, 2022). "Meanwhile, we also found UGRP1 slightly increased mRNA levels of Il6, Il1b and Tnfa in PEMs without infection of S. pneumoniae." (PMID 35652821, 2022). "Even in the case of IL-6, it was observed that IL-6 decreased to a very low value after 3 days of hospitalization in the presence of infection, but increased with severe changes in the absence of infection." (PMID 36555941, 2022). "S. oralis infections as single species caused a significant increase in the expression of IL-1α, IL-6, IL-12 (p40), CXCL1/KC, CCL5/RANTES, and CCL11 compared to infection without implants." (PMID 35203495, 2022). "Levels of proinflammatory cytokines in Mtb-infected lung lysates, including IL-6 and TNF, were significantly upregulated, while IL-10 levels in the coinfected group were comparable with those in the Mtb-infected group at 7 days post LCMV Arm infection." (PMID 35672321, 2022). "According to this prediction and to the observation that the virus can activate monocyte‐derived DCs following abortive infection, we demonstrated that SARS‐CoV‐2 can directly induce significant downregulation of MHCII surface expression and the upregulation of IL‐6 in both DC2s and DC3s." (PMID 34333764, 2022). "The results showed that the production of IL-6 in MDCK cells increased at 72 h post infection with H1N1, while increased production of MIP-1α was observed at 48 h post infection; however, effective suppression of both was achieved by combined treatment with alloferon and zanamivir." (PMID 36614125, 2022). "Interestingly, organoid infection with SARS-CoV-2 at an MOI of 1 significantly increased expression of the proinflammatory cytokines Tnf and Il6 at 48 hpi, and Il6 remained elevated at 72 hpi." (PMID 36561186, 2022). "For example, our early human subject study demonstrated that zinc supplement (45 mg zinc daily for 6–12 months) decreased plasma level of IL-6, other inflammatory cytokines, and oxidative stress markers in elderly subjects and SCD patients along with the reduction of infection incidence." (PMID 36290585, 2022). "Clearly, before IL-6 antagonist administration, viral and bacterial infections, especially latent or immunosuppressing infections, should be ruled out." (PMID 35645219, 2022). "After 24 h infection, PRV strongly induced NO, IL-6 and TNF-α expression in the BV-2." (PMID 35324841, 2022). "In addition, mice treated with anti-C5aR Ab had lower serum concentrations of ALT and inflammatory cytokines, especially TNF-α and IL-6, 48 hrs after MHV-3 infection, consistent with our prior observations made by administrating C3aR antagonist." (PMID 35573780, 2022). "Gene expression levels of IL6 were not markedly altered upon infection with H5N1 HPAIV in any cell type, but IL8 fold change values were higher in chicken than in duck cells." (PMID 35062369, 2022).
infection (continued). "In addition, ASFV-ΔH240R infection induced higher expression of proinflammatory cytokines, including IL-1β, IL-6, TNF-α, and C-X-C motif chemokine ligand 8, in PAMs than did ASFV-WT infection." (PMID 36326277, 2022). "Infection of Vero E6 cells with the SARS-CoV-2 virus significantly reduced the expression of selenoproteins GPX4, TXNRD3, SELENOS, SELENOK, SELENOF, and SELENOM, while the level of the inflammatory cytokine IL-6 increased against this background." (PMID 35216476, 2022). "For instance, ST infection could recruit the inflammatory monocytes to the CNS in mice; Salmonella-derived LPS markedly activated the expression of TNF-α, IL-1β, and IL-6 in microglia and astrocytes in vitro." (PMID 35967771, 2022). "Moreover, other inflammatory factors, such as IL-6 and TNF-α, were also found to be upregulated in ECHO 11-infected THP-1 cells and BMDMs, confirming that ECHO 11 infection induces inflammation." (PMID 36026486, 2022). "In the context of infection, adipocytes may also be the source of FFA, but perhaps indirectly via the inflammatory cytokine, interleukin 6 (IL6)." (PMID 35528134, 2022). "Cord blood leptin was unaltered in the presence of clinically diagnosed infection but correlated with IL-6 in the absence of infection." (PMID 35197933, 2022). "Infection of intestinal epithelial cells with S. Typhimurium significantly induced the secretion of IL-6 compared with controls (i.e., non-infected cells)." (PMID 35630380, 2022). "CRP and IL-6 levels continued to increase until 14 days after admission in patients who died within 30 days, which reflects more severe infection or non-infectious inflammatory conditions." (PMID 36555941, 2022). "The laboratory results upon admission showed high CRP (205.11 mg/L), PCT (3.06 ng/mL), and IL6 (1276 pg/mL) values, suggestive of an infection, but the BALF and whole blood culture were both negative." (PMID 35847093, 2022). "IL-10 and IFNγ CD4+ cells are important for a chronic, nonresolving infection status, and together with the elevated TNFα and IL-6 expression, these data fit well with the enhanced and prolonged inflammation in the colons of AOM/DSS-treated CerS4 LCK/Cre mice." (PMID 35163788, 2022). "Additionally, after infection with three PRV strains, the transcriptional levels of IL-1β, IL-6, TNF-α, and IFN-β were highest at 3 h, 6 h, 9 h, and 12 h, respectively, and then gradually decreased." (PMID 35458442, 2022). "Increased production of IL-6 in MDCK and A549 cells was observed after infection with H1N1; however, production of IL-6 showed a marked decreased after treatment with combination alloferon/zanamivir that was significantly greater than that after treatment with alloferon or zanamivir alone." (PMID 36614125, 2022). "Upon infection with LPS, the activation of PI3K/AKT signaling pathway activates nuclear factor-kappa B (NF-κB) and inhibits protein-1 (AP-1) and ultimately increases the expression of inflammatory cytokines such as IL-6 and TNF-α." (PMID 35295341, 2022). "Both TMEV-susceptible (e.g., SJL/J) and TMEV-resistant (e.g., C57BL/6J) inbred mouse strains mount a strong pro-inflammatory cytokine response within the CNS during the acute phase of infection, for example as shown by increased transcript levels for cytokines IFN-γ, IL-1, IL-6, IL-12p40, and TNF-α." (PMID 35805128, 2022). "In addition, cytokines, including IL-6/IL-10/TNF-α/IFN-γ can be used for rapid and timely diagnosis of infection in children with hematological malignancy." (PMID 35463642, 2022). "The production of inflammatory cytokines (IL-6, IL-8, and IL-1β) and the neutrophilic response during UPEC infection are critical for host clearance of infection; however, an excessive inflammatory response to UPEC infection can result in deleterious renal pathology." (PMID 35925892, 2022).